CRP (C-reactive protein)
Diseases named in the same sentence as CRP in open-access papers (continued):
Sharing a sentence is not in itself a finding about the gene and the disease.
Encephalopathy (23 papers, 2013 to 2026). Encephalopathy is a term that means brain disease, damage, or malfunction. "For example, a recent study found that a DNAm-based proxy of CRP correlates with inflammation burden and MRI markers of encephalopathy of prematurity after preterm birth." (PMID 38528588, 2024). "C-reactive protein is an acute phase protein whose levels increase with the severity of encephalopathy." (PMID 33141256, 2021). "Another study correlates the CRP levels with encephalopathy occurrence in cirrhotic patients, and many others have described the relevance of inflammation in HE neural physiopathology." (PMID 23324408, 2013). "Future studies should compare the strength of association between CRP and ADC values between different pathogen-driven encephalopathy groups to be able to conclude if these associations are specific to certain pathogens or to pathogen-related encephalopathies in general." (PMID 34709472, 2021). "Patients with HUS have a rise in C-reactive protein, neutrophilia, and an increase in circulating proinflammatory cytokines, indicating that the impact of hemorrhagic colitis may be important for the subsequent development of severe complications, such as HUS and encephalopathy." (PMID 31288487, 2019). "Patients with HUS demonstrate a rise in c-reactive protein, neutrophilia and an increase in circulating proinflammatory cytokines, indicating that the impact of hemorrhagic colitis may be important for the subsequent development of severe complications, such as HUS and encephalopathy." (PMID 29253906, 2017). "In this case, the patient had raised levels of TNF-alpha, low lymphocyte count and a raised CRP in the absence of any cerebrospinal fluid evidence of virus or MRI and EEG evidence of an encephalopathy." (PMID 32696735, 2020).
hepatitis C (23 papers, 2012 to 2025). "Yet, it was previously reported that anti-CRP autoantibodies have been reported in hepatitis C cases, a fact that raises further diagnostic questions for its lower levels in that condition." (PMID 37873776, 2023). "As chronic infections, such as HIV and hepatitis C are known causes of CRP elevations above 10 mg/l in African populations, we performed sensitivity analysis by excluding all participants above this CRP threshold." (PMID 34478414, 2022). "Similarly, hepatitis C has been associated with reduced CRP levels in humans." (PMID 26317021, 2013). "PABPC4, another associated protein of Lnc-PCIR, which has been demonstrated related to the inflammatory biomarker (C-reactive protein) and anti-hepatitis C response, is expressed at a higher level in tumor tissues." (PMID 34012913, 2021). "Other factors included Hepatitis C serology and highly sensitive C-reactive protein." (PMID 35815221, 2022). "This is because CRP is mainly produced by the liver and hepatitis C infection, which was positive in all HIV+ study participants, could lead to significant liver damage." (PMID 29097998, 2017). "The exact mechanism for that hepatitis C linked with lower hs-CRP level is not known." (PMID 22645408, 2012). "The results indicated that SGPT, LDH, TBIL, DBIL, CRP, ESR, ferritin, neutrophil, lymphocyte, and PLR factors served as reliable predictors for hepatitis C infection (area under the ROC curves (AUCs) = 0.803–1.000)." (PMID 39569979, 2024). "CRP did not predict cardiovascular disease, but CRP levels were reduced by 50% in animals with hepatitis C infection and showed inverse relationships with 2 liver function enzymes." (PMID 26317021, 2013). "However, the levels of CRP and IL6 reported in previous studies with less stringent exclusion criteria were much higher and the proportion of participants with known co-morbidities such as hepatitis C was about 20%." (PMID 25888119, 2015).
hydronephrosis (23 papers, 2013 to 2026). Collection of urine in the renal pelvis that results in dilatation of the renal pelvis and calyces. "Renoureteral lithiasis over 8 mm in pregnancy can cause hydronephrosis with renal colic and superinfection, a high degree of hydronephrosis, fever, leukocytosis, elevated creatinine, and CRP." (PMID 39768572, 2024). "Data on age, sex, body mass index, the presence of associated hydronephrosis/stranding on images, ureteral side, stone location, medical history, serum blood count, creatinine, C-reactive protein, and vital signs were obtained upon admission." (PMID 35821517, 2022). "Imaging unveiled ureterolithiasis and hydronephrosis, while serum chemistry displayed elevated creatinine, blood urea nitrogen, and C-reactive protein." (PMID 40144524, 2025). "Radiological parameters (stone size, location, and hydronephrosis) and hematological markers (C-reactive protein (CRP) and neutrophil-to-lymphocyte ratio (NLR)) were assessed as predictors of treatment success." (PMID 39310590, 2024). "In the testing set, the median (Q1, Q3) of CRP for the pyonephrosis group was 95.41 (56.53, 154.69) and the hydronephrosis group was 9.53 (4.98, 40.76)." (PMID 38896174, 2024). "According to the current literature, serum CRP concentration, pyuria, hydronephrosis, and helical CTS findings of perinephric fat stranding and the tissue-rim sign related to inflammatory changes are negative predictors for spontaneous stone passage." (PMID 35767556, 2022). "There were significant differences between the two groups with respect to the duration of pain, fever, WBC count, CRP level, ureter stone size, hydronephrosis, and stone location." (PMID 35255882, 2022). "Disease progression can be monitored by a regular evaluation of CRP and creatinine levels, as well as radiological imaging via CT, MRI, or ultrasound (to monitor hydronephrosis)." (PMID 28379669, 2017). "More recent studies have suggested other predictive factors, e.g. C-reactive protein (CRP), hydronephrosis and side of the stone." (PMID 28593428, 2017). "Stone location, side, hydronephrosis, CRP, medical expulsion therapy (MET) and all follow-up radiology until stone expulsion or 26 weeks were recorded." (PMID 28593428, 2017). "Examples involve ureteral density in non-contrast computed tomography (NCCT), ureteral wall thickness (UWT), C-reactive protein (CRP), erythrocyte sedimentation rate (ESR), grade of hydronephrosis, age, stone position, and the ratio of CT attenuation value of the ureter above to below stones." (PMID 41509097, 2026). "The univariate analysis showed significant differences in sex, fever, history of urological surgery, WBCC, neutrophils, serum CRP, serum albumin, urine leukocyte, WBCC, grade of hydronephrosis, CT value of hydronephrosis, and thick wall of the renal pelvis (P < .05) between 2 groups." (PMID 36181040, 2022). "The limitations of our study include its retrospective nature, limited sample size, and lack of assessment of parameters such as CRP, presence of hydronephrosis, size of the primary tumor, and number of foci." (PMID 23606819, 2013). "After adjustment in a multivariable Cox regression model, the eGFR and level of creatinine at diagnosis were regarded as prognostic factors (p = 0.002 and p = 0.067 respectively), rather than the level of ESR, CRP, IgG, HGB, or hydronephrosis." (PMID 39717179, 2024).
nephritis (23 papers, 2009 to 2025). Inflammation of renal tissue. "The risk factors of infection in patients with SLE include the overall disease activity, higher C-reactive protein levels, higher anti-dsDNA levels, low complement levels, nephritis, daily dose of prednisone>10 mg, and others." (PMID 37324478, 2023). "Although most manifestations of SLE including nephritis are inflammatory, C-reactive protein (CRP) elevation is more related to infections than to disease activity in SLE." (PMID 32244481, 2020). "In fact, the high prevalence of serum anti-modified CRP (mCRP) autoantibodies were detected in TINU syndrome in active phase of nephritis." (PMID 29850203, 2018). "S Yamamoto, T Shida, S Miyaji, H Santsuka, H Fujise, K Mukawa, E Furukawa, T Nagae and M Naiki reported increased and decreased CRP serum values in dogs with different disorders such as enteritis, eye diseases and nephritis." (PMID 26746899, 2016). "We observed that the CRP was significantly increased in both NS and nephritis groups, which may be responsible for the increased CD3+CD4−CD8+T cell proportion." (PMID 36625011, 2022). "Moreover, inflammatory markers including ESR and CRP were elevated in both nephritis (p < 0.001) and non-nephritis patients (p < 0.001 and p = 0.002, respectively) versus controls." (PMID 34572591, 2021). "In patients with nephritis, anti-CRP Abs were also more frequent." (PMID 33664737, 2020). "We have previously demonstrated that the occurrence of autoantibodies against the tissue-based/monomeric CRP is a common finding in SLE, particularly in patients with nephritis, and that anti-CRP antibody levels correlate with SLE disease activity index, anti-dsDNA and complement components." (PMID 20003354, 2009). "A study by Soliman et al33 showed that NLR was much higher in SLE patients with active disease and with nephritis; NLR was positively correlated with ESR, CRP, and SLEDAI but negatively correlated with C4." (PMID 31978275, 2020). "The frequency of anti-CRP Abs was also more frequent in patients with nephritis (27% and 13% in patients with or without nephritis, respectively)." (PMID 33664737, 2020). "Collectively, these data suggest that anti-CRP Abs reflect SLE activity rather than a specific pattern of SLE nephritis." (PMID 33664737, 2020). "However, CRP can inhibit experimental allergic encephalomyelitis (EAE) and kidney inflammation by macrophage- and IL-10-dependent mechanisms." (PMID 28619036, 2017). "Patients with proliferative nephritis (WHO class III or IV) had a greater reduction of anti-CRP antibody levels compared with patients with membranous (WHO class V) nephritis, although this was not statistically significant (P = 0.08)." (PMID 20003354, 2009). "Similarly, another studies found that age over six years, purpura in atypical locations, and positive fecal occult blood tests were associated with nephritis, whereas WBC count, hemoglobin concentration, and CRP levels did not significantly predict renal involvement." (PMID 40310537, 2025). "Besides, the patients with nephritis were in the inflammatory status, and inflammation acted as an influencing factor has been clarified by many studies, which found that Scys-C was associated with many inflammatory markers like IL-6, TNF-α but not with C-reactive protein (CRP)." (PMID 24465871, 2014).
post-traumatic stress disorder (23 papers, 2017 to 2025). An anxiety disorder precipitated by an experience of intense fear or horror while exposed to a traumatic (especially life-threatening) event. "Another condition that can cause the secretion of a C-reactive protein is post-traumatic stress disorder since it can cause hormone dysregulation and alterations in inflammatory signaling." (PMID 39199534, 2024). "Methylation of AIM2 locus was previously reported to be related to trauma exposure, post-traumatic stress disorder, and C-reactive protein associations." (PMID 36072791, 2022). "AIM2 methylation has also been associated with C-reactive protein (C-RP) polymorphism and C-RP levels in people with post-traumatic stress disorder (PTSD)." (PMID 33643304, 2020). "A variety of studies confirms an association of elevated CRP with depressive symptoms, post-traumatic stress disorder (PTSD), and psychosis as well as with perceived psychosocial stress in adults." (PMID 34975902, 2021). "Mood and anxiety disorders, such as post-traumatic stress disorder (PTSD), are associated with elevated C-reactive protein levels, which in turn are associated with altered morphology and altered activation of the threat circuit." (PMID 40728957, 2025). "Miscellaneous diseases and traits that were associated with CYP3A4 include cytokine levels, post-traumatic stress disorder (PTSD), heel bone mineral density, height, offspring birth weight, lymphocyte count, C-reactive protein levels, and triglyceride levels." (PMID 39457450, 2024). "Links between CRP and posttraumatic stress disorder (PTSD) or cognitive function also remain unclear." (PMID 30797045, 2020). "For example, future research might benefit from including biophysical (e.g., cortisol, C-reactive protein) and psychosocial (e.g., posttraumatic stress disorder) measures over time." (PMID 31619166, 2019). "Methylation of the AIM2 gene at the site cg10636246 drives the relationship between trauma exposure, posttraumatic stress disorder (PTSD), the level of C-reactive protein (CRP) and other inflammatory mediators, such as IL-6, IL-10, and TNF-α, in the body." (PMID 36742336, 2023). "Moreover, physically healthy soldiers with combat experience also exhibited increased plasma C-reactive-protein (CRP), an acute-phase protein produced during inflammation, which further correlated with depressive and posttraumatic stress disorder assessment scores." (PMID 29403490, 2018).
acute pyelonephritis (22 papers, 2010 to 2025). "Acute pyelonephritis was diagnosed in 33/55 infants by a positive first DMSA scan within 7 days of inclusion (mean CRP level, 96.9 mg/L)." (PMID 40856487, 2025). "The aims of this retrospective cross‐sectional study were 1) to evaluate serum CRP in dogs with bacterial cystitis (BC), acute pyelonephritis (AP) and acute bacterial prostatitis (ABPR); 2) to compare serum CRP among these groups." (PMID 39535393, 2024). "In a previous study conducted with children diagnosed with acute pyelonephritis and lower UTIs, the diagnostic values of serum PCT and interleukin (IL)-1β levels were compared with sedimentation rate and CRP levels." (PMID 38611690, 2024). "CT results confirmed acute pyelonephritis accompanied by periportal edema and elevated levels of hepatic enzymes and C-reactive protein." (PMID 38535058, 2024). "Serum CRP concentrations at the diagnosis accurately differentiate dogs with bacterial cystitis from those with acute pyelonephritis and/or prostatitis." (PMID 39535393, 2024). "In dogs with UTI and markedly elevated CRP the presence of acute pyelonephritis or acute prostatitis should be suspected." (PMID 39535393, 2024). "With these findings, patients (30, 88.24%) diagnosed with acute pyelonephritis had CRP levels >100 mg/L, while patients (22, 56.41%) diagnosed with cystitis had CRP levels ranging between 3-50 mg/L." (PMID 35915684, 2022). "Studies in the literature show that CRP level is an important marker for acute pyelonephritis in patients with ureteral stones." (PMID 35464554, 2022). "The PCT and CRP values in children with acute pyelonephritis were significantly higher than those in children with lower urinary tract infection (3.90 ± 3.51 ng/ml and 68.17 ± 39.42 mg/l vs. 0.48 ± 0.39 ng/ml and 21.39 ± 14.92 mg/l)." (PMID 24886302, 2014). "Some clinical studies have examined the significance of laboratory data, including CRP, to diagnose acute pyelonephritis in children." (PMID 25488491, 2014). "Since several studies found that CRP values at admission in clinically diagnosed acute pyelonephritis were higher in patients with scars on 99mTc-dimercaptosuccinic acid (DMSA) scintigraphy, we could hypothesize that the risk of renal damage would be increased in this patients sample." (PMID 36109739, 2022). "Our results were in accord with past reports indicating that CRP had a lower specificity for identifying children with renal parenchymal involvement, whereas a cut‐off value of 1.0 ng/ml of PCT had been shown to be predictive of acute pyelonephritis in young children." (PMID 35349730, 2022).
celiac disease (22 papers, 2014 to 2025). An autoimmune genetic disorder with an unknown pattern of inheritance that primarily affects the digestive tract. "In addition, all 3 children had extensive work-ups including normal hemoglobin, sedimentation rate, C-reactive protein, stool studies, endoscopy and histology, suggesting bacterial infection, parasite infestation, intestinal inflammation and celiac disease were unlikely causes." (PMID 24433566, 2014). "Another recent study demonstrated that an increased CRP/albumin ratio can predict coronary microvascular dysfunction better than CRP or albumin alone in patients with celiac disease." (PMID 33453709, 2021). "In the same group of children, CRP levels were higher compared with children with celiac disease (CD1) with relatively high TAC and low TOC levels, yet still within the range of reference standards." (PMID 29854070, 2018). "In our study of patients with active disease, the prevalence of LTA was highest in patients with the highest CRP (48% when CRP >58 mg/L) and this is in line with what is observed in patients with coeliac disease." (PMID 27900523, 2017). "These guidelines suggest a positive diagnostic strategy within a symptom-based approach, comprehensive of psychological comorbidities assessment, alarm signs and symptoms’ exclusion, testing for celiac disease and, under specific circumstances, fecal calprotectin and C-reactive protein." (PMID 38486305, 2024). "The laboratory tests most commonly performed in 2015 (TSH, CRP, serum test for coeliac disease) mostly complied with the recommended assessment to eliminate differential diagnoses, particularly in the case of IBS-D or IBS-M, but they were repeated too frequently before or even after the diagnosis." (PMID 31248366, 2019). "A recent work confirmed that anti-integrin αvβ6 IgG performed better than calprotectin and C-reactive protein (CRP) in distinguishing UC from diseased controls (including IBS, celiac disease, and other conditions)." (PMID 40918109, 2025). "The year before, 65% had at least one CRP dosage (13% three or more), 58% a TSH dosage (7%) and 8% a test for coeliac diseases (1%) and the year after: 44% (8%), 43% (5%) and 3% (0.3%)." (PMID 31248366, 2019). "The results suggest that aerobic exercise in association with fish oil supplementation is more capable of modulating CRP when compared to only fish oil supplementation in celiac disease patients or the absence of interventions in healthy people." (PMID 35910449, 2022). "Haematinic tests, in addition to testing for coeliac disease, helicobacter pylori, vitamin D, CRP and HbA1c may also be requested for more non-specific symptoms including fatigue, musculoskeletal issues or abdominal symptoms." (PMID 39448080, 2024).